TIMP2 (TIMP metallopeptidase inhibitor 2)
Diseases named in the same sentence as TIMP2 in open-access papers (continued):
Sharing a sentence is not in itself a finding about the gene and the disease.
diabetic cardiomyopathy (1 paper, 2012). Diabetic cardiomyopathy is a disorder of the heart muscle in people with diabetes. "Our results, demonstrated that ALA treatment ameliorated cardiac dysfunction, decreased LV Type I and III collagen deposition, reduced TIMP-2 and increased MMP-2 activity in STZ-induced diabetic cardiomyopathy." (PMID 22713251, 2012).
diabetic retinopathy (1 paper, 2020). "TIMP-2 is an endogenous inhibitor of matrix metalloproteinase-2 and may act as a protector to reduce the loss of capillary cells resulting in the development of diabetic retinopathy." (PMID 33323553, 2020).
endometrial adenocarcinoma (1 paper, 2020). "The miR-27-FOXO1 tandem induces apoptosis, and miR-200b inhibits TIMP2 expression and affects metastasis of endometrial adenocarcinoma." (PMID 32760226, 2020).
endophthalmitis (1 paper, 2025). An infectious process affecting the internal structures of the eye. "Multiple regression analysis revealed that the longer the duration of DM and the endophthalmitis diagnosis was associated with TIMP2/MMP2 ratio." (PMID 41009516, 2025). "TIMP2 concentrations differed significantly (p = 0.003), with the endophthalmitis group exhibiting the highest levels (64,800 pg/mg)." (PMID 41009516, 2025). "Moreover, endophthalmitis cases exhibited higher levels of TIMP2, whereas vitreomacular interface disorders showed lower levels of TIMP2." (PMID 41009516, 2025). "Furthermore, preoperative diagnostic retinal pathology significantly influenced the TIMP2/MMP2 ratio, in which the highest ratio was observed in patients with endophthalmitis (6.49) and the lowest ratio was observed in patients with dropped IOL/crystalline lens (1.46, p = 0.004)." (PMID 41009516, 2025). "Significantly, TIMP2 and TIMP2/MMP2 levels were highest in the endophthalmitis group, whereas MMP2 levels were highest in the dropped crystalline lenses group." (PMID 41009516, 2025). "The TIMP2/MMP2 ratio varied significantly among groups (p = 0.004), being highest in the endophthalmitis group (6.49) and lowest in the dropped IOL/lens cases (1.46)." (PMID 41009516, 2025). "Patients with endophthalmitis and advanced PDR had the highest levels of TIMP2 (64,800.0 pg/mL and 29,310.8 pg/mL, respectively, p = 0.003)." (PMID 41009516, 2025).
gastroduodenal ulcer (1 paper, 2010). "This is the first report to show that there is no direct association between the genotypes of TIMP-1 372 at exon 5 and TIMP-2 at promoter -418, and the presence of gastroduodenal ulcers." (PMID 20707923, 2010). "Although MMP activity is in general counteracted by endogenous tissue inhibitors (TIMPs), there remains no data to check whether TIMP-1 and TIMP-2 SNP genotypes relate to the risk of gastroduodenal ulcer after H. pylori-infection." (PMID 20707923, 2010).
gestational diabetes (1 paper, 2010). Carbohydrate intolerance first diagnosed during pregnancy. "TIMP-2 levels are elevated in the third trimester in women with impaired glucose tolerance and gestational diabetes." (PMID 20565712, 2010).
glomerulonephritis (1 paper, 2024). A renal disorder characterized by damage in the glomeruli. "On the contrary, while the cause of CKD was glomerulonephritis, decreased concentrations of this metalloproteinase were observed in both studied groups, whereas the reduction in TIMP-2 was seen only in the β-blockers (−) group." (PMID 38610612, 2024).
head and neck cancer (1 paper, 2019). A primary or metastatic malignant neoplasm affecting the head and neck. "In numerous reports regarding head and neck cancers, the present correlations are emphasized between the changes in the expression of MMP-2, MMP-9, TIMP-1, and TIMP-2 with tumor progression or its clinical stage." (PMID 31223594, 2019).
hematoma (1 paper, 2015). A hematoma is a collection of blood from a vascular structure into an extravascular space. "This is the first study proposing that MMP-2 and TIMP-2 genotypes are associated with the SDICH susceptibility and hematoma size with age and gender difference." (PMID 26551785, 2015). "This study aimed to discuss relationship of MMP-2 and TIMP-2 to spontaneous deep ICH (SDICH) susceptibility and hematoma size." (PMID 26551785, 2015).
hemorrhage (1 paper, 2015). Loss of blood from the vascular compartment to the exterior or into nonvascular body space as a result of rupture or severance of the blood vessels. "In addition, TIMP-2 promoter variants were associated with hemorrhage size in female patients, in which rs7503607 variant increased hemorrhage size while rs7503726 variant decreased it." (PMID 26551785, 2015). "This study suggested that hemorrhage size might be affected by TIMP-2 promoter variants in the SDICH patients." (PMID 26551785, 2015).
Hyperinsulinemia (1 paper, 2023). An increased concentration of insulin in the blood. "BCL2L11 (FCHG, ins = 1.16), CDKN1A (FCHG, ins = 0.97) and TIMP2 levels (FCHG, ins = 1.50) were not affected by hyperinsulinemia." (PMID 37313172, 2023).
hypertrophic cardiomyopathy (1 paper, 2020). A condition in which the myocardium is hypertrophied without an obvious cause. "GC samples in the FRMD6 and TIMP2 high expression group were significantly enriched for hypertrophic cardiomyopathy (HCM)." (PMID 32095347, 2020).
inclusion body myositis (1 paper, 2007). A slowly progressive degenerative inflammatory disorder of skeletal muscles characterized by late onset weakness of specific muscles and distinctive histopathological features. "One report mentioned that expression of TIMP-1 and TIMP-2 mRNA levels were not different between inflammatory myopathies/inclusion body myositis and muscular dystrophy." (PMID 17598883, 2007).
infarcts (1 paper, 2023). "According to these observations, in our study, by analyzing the presence of cerebral lacunar infarcts detected by MRI, we demonstrate a positive and significant independent association between MMP-2, TIMP-1, TIMP-2, TIMP-3 and the presence of the lesions." (PMID 37959331, 2023).
infertile (1 paper, 2015). "In infertile patients, an increase in the follicular TIMP-1, but not TIMP-2, level was detected compared with that in the normally ovulating control group." (PMID 26337061, 2015).
intracranial aneurysm (1 paper, 2015). "In total, there are five MS genes related to intracranial aneurysm (CASP3, ENG, TIMP1, TIMP2, and TIMP3)." (PMID 26486520, 2015).
intraventricular haemorrhage (1 paper, 2026). "The objective of the present study is to examine the association between the presence of various forms of matrix metalloproteinase genes (MMP-1, MMP-9, TIMP-1 and TIMP-2) and their tissue inhibitors, and the incidence of intraventricular haemorrhage (IVH) in premature neonates." (PMID 41898459, 2026).
Iron deficiency (1 paper, 2023). "Iron deficiency decreased their levels at 24 h, while FKN addition reversed this effect, but later iron deficiency increased PTGER2 and decreased TIMP2, FKN in turn decreased PTGER2 and increased TIMP2 compared to DFO treatments." (PMID 37175630, 2023).
juvenile idiopathic arthritis (1 paper, 2019). Juvenile idiopathic arthritis (JIA) is the term used to describe a group of inflammatory articular disorders of unknown cause that begin before the age of 16 and last over 6 weeks. "The aim of this study was to evaluate the concentration of MMP-2, MMP-8, and MMP-9 and their inhibitors TIMP-1 and TIMP-2 of unstimulated whole saliva (UWS) in correlation with the oral health in juvenile idiopathic arthritis (JIA) children." (PMID 31781639, 2019).
kidney transplant (1 paper, 2017). A surgical procedure in which one or both kidneys from a donor are implanted into a recipient. "We collected urine samples of 33 kidney transplant recipients and 14 non-transplanted patients who all had AKI (stages 1–3 according to KDIGO), and measured [IGFBP7]x[TIMP-2] using the NephroCheck® Astute1 40 TM meter." (PMID 29145491, 2017).
leukoplakia (1 paper, 2014). A white patch or plaque on a mucous membrane that cannot be characterized clinically or pathologically as any other disease. "In this study we sought to determine the expression and the correlation of MMP-2 and TIMP-2 in oral leukoplakia through different grades of oral epithelial dysplasia as these proteases appear to be important in the early phases of cancer progression including local invasion and micrometastasis." (PMID 24591757, 2014).
Lewis Lung Carcinoma (1 paper, 2023). "To assess whether a loss of function mutation of the Timp2 gene alters primary tumor growth, we employed an orthotropic murine model of Lewis lung carcinoma using the LL/2-Luc2 cell line." (PMID 38234759, 2023). "We characterized this new murine line and developed both orthotopic and heterotopic, syngeneic models of Lewis Lung Carcinoma to determine the effect of TIMP2 on the TME during lung tumor progression and the metastatic niche formation." (PMID 38234759, 2023).
limb ischemia (1 paper, 2016). A ischemia that involves the limb. "The mechanisms responsible for this effect are still unclear, but we have proposed that limb ischemia releases damage-associated molecular patterns that signal the kidney to release TIMP-2 and IGFBP7 as part of an “alarm” that protects cells from subsequent injury." (PMID 27245788, 2016).
lung squamous cell carcinoma (1 paper, 2019). "TIMP2 displays less dynamic, although significant changes in expression at similar cancer sites (bladder, breast, lung squamous cell carcinoma (SCC) and prostate) when compared to normal tissues." (PMID 31882975, 2019).
Lymphatic Metastasis (1 paper, 2014). Transfer of a neoplasm from its primary site to lymph nodes or to distant parts of the body by way of the lymphatic system. "Positive expression of TIMP-2 was associated with lymphatic metastasis, clinical staging and T classification." (PMID 24829764, 2014). "Positive expression of TIMP-2 was correlated with lymphatic metastasis, clinical staging and T classification." (PMID 24829764, 2014). "The positive rate of TIMP-2 expression in patients with lymphatic metastasis was significantly lower than those without it (χ2 = 26.74, P = 0.002), which significantly reduced with increasing clinical stage and T classification (P < 0.05)." (PMID 24829764, 2014). "The positive rate of TIMP-2 expression in patients with lymphatic metastasis was significantly lower than those without it (χ2 = 26.74, P = 0.002), and the rate significantly reduced with increasing clinical stages and T classification (P < 0.05)." (PMID 24829764, 2014).
malignant mesothelioma (1 paper, 2013). A malignant neoplasm of the pleura or peritoneum, arising from mesothelial cells. "Malignant mesothelioma MSTO-211H cells did not secrete u-PA; however, MMP-9 secretion by MSTO-211H was inhibited by NM and secretion of TIMP-2 was enhanced by NM." (PMID 23563849, 2013).
malignant rhabdoid tumor (1 paper, 2022). "Membrane-type 1 matrix metalloproteinase (MT1-MMP/MMP-14) and tissue inhibitor of metalloproteinases-2 (TIMP-2) were highly expressed in these malignant rhabdoid tumor cells, indicating their invasive phenotypes." (PMID 35954348, 2022).
medulloblastoma (1 paper, 2013). A malignant, invasive embryonal neoplasm arising from the cerebellum. "Also, miR-21 is up-regulated in medulloblastoma cells and its down-regulation increased the expression of negative modulators of cancer cell migration, E-Cadherin and TIMP2 proteins and their positive regulator PDCD4 which results in decreased motility of medulloblastoma." (PMID 23391314, 2013).
metastatic colorectal cancer (1 paper, 1997). "Exploration of TIMP-2 expression is valuable for the discrimination between macroscopically localized and metastatic colorectal cancer, but it cannot predict which of the potentially cured patients are likely to have micrometastases." (PMID 9310250, 1997).
Moyamoya disease (1 paper, 2014). Moyamoya disease (MMD) is a rare intracranial arteriopathy involving progressive stenosis of the cerebral vasculature located at the base of the brain causing transient ischemic attacks or strokes. "The presence of a G/C heterozygous genotype at position -418 in the promoter of the tissue inhibitor of metalloproteinase-2 (TIMP-2) gene has been proposed as a genetic predisposing factor for moyamoya disease (MMD), but this association is debated." (PMID 25280484, 2014).
mucinous ovarian cancer (1 paper, 2020). An invasive malignant neoplasm that arises from the ovary and is characterized by the presence of malignant epithelial cells that contain intracytoplasmic mucin and may resemble the epithelial cells of the endocervix or gastrointestinal tract. "In addition, increased expression levels of MMPs, including MMP-2, MMP-7, and MMP-9, as well as TIMPs, including TIMP-1 and TIMP-2, were observed in mucinous ovarian cancer compared with those in serous ovarian cancer." (PMID 32197606, 2020).
muscle atrophy (1 paper, 2017). The loss of muscle tissue due to inactivity or disease. "Therefore, data on the balance between MMP-2 and TIMP-2 may provide useful information for evaluating the effects of low-frequency ES on reducing early-stage muscle atrophy and capillary regression in denervated muscles." (PMID 28497057, 2017).
myasthenia gravis (1 paper, 2022). Myasthenia gravis (MG) is a rare, clinically heterogeneous, autoimmune disorder of the neuromuscular junction characterized by fatigable weakness of voluntary muscles. "We evaluated the plasma levels of MMP-9 and MMP-2 and their tissue inhibitors TIMP-1 and TIMP-2 in a patients’ cohort with generalized myasthenia gravis (MG)." (PMID 36358365, 2022).
myocarditis (1 paper, 2020). Myocarditis is a condition that is characterized by inflammation of the heart muscle (myocardium). "While there are no significant changes in total ventricle fibrosis, eosinophil depletion post-myocarditis leads to decreased expression of MMP2 and tissue inhibitor of metalloproteinases 2 (TIMP2)." (PMID 32322219, 2020).
oncocytoma (1 paper, 2014). "TIMP-2 was positive in all (100%) the individuals with oncocytoma (range, 184–445 ng/ml; mean ± SD, 300±110 ng/ml) and in 15/16 (94%) of the ccRCC patients (range, 52–452 ng/ml; mean ± SD, 248±105 ng/ml)." (PMID 24520285, 2014). "The mean values for MMP-2 and -9 and TIMP-2 in the positive urine specimens were similar in the ccRCC and oncocytoma patients, whereas the mean value of TIMP-1 was higher in the ccRCC patients compared with that of the oncocytoma patients." (PMID 24520285, 2014). "Finally, TIMP-2 was detected in 3/4 (75%) of the oncocytoma patients and in 7/9 (78%) of the ccRCC patients." (PMID 24520285, 2014).
Oral ulcer (1 paper, 2025). Erosion of the mucous mebrane of the mouth with local excavation of the surface, resulting from the sloughing of inflammatory necrotic tissue. "The decrease in TIMP-2 levels, which support tissue regeneration, may accelerate the tissue destruction process and the disruption of ECM homeostasis with the triggering of the inflammatory response after an oral ulcer." (PMID 40283497, 2025).
organizing pneumonia (1 paper, 2016). "Gene expression profiling of human and murine organizing pneumonia lesions showed in part comparable expression levels of pivotal genes, notably of TGFB1/Tgfb1, TIMP1/Timp1, TIMP2/Timp2, COL3A1/Col3a1, CXCL12/Cxcl12, MMP2/Mmp2 and IL6/Il6." (PMID 27282780, 2016).
osteonecrosis of the femoral head (1 paper, 2021). "The SNP rs4789936 on TIMP-2 was observed to decrease the risk of alcohol-induced osteonecrosis of the femoral head (ONFH) in the Chinese Han population under allele, dominant, overdominant, and log-additive models after adjusting for age and sex." (PMID 35087566, 2021).
osteoporosis (1 paper, 2025). A condition of reduced bone mass, with decreased cortical thickness and a decrease in the number and size of the trabeculae of cancellous bone (but normal chemical composition), resulting in increased fracture incidence. "The enzyme analysis results of all these studies revealed that MMP2, MMP9, TIMP1, and TIMP2 were low and cathepsin K was high in MPS III patients, and that the patients had low bone density and increased osteoporosis risk." (PMID 40104299, 2025).
paroxysmal AF (1 paper, 2022). "Therefore, as shown the best results in this phase, TIMP-2 and ST-2 were selected to be tested in phase II, together with NT-proBNP, which had previously shown promising results, even to detect paroxysmal AF." (PMID 35998199, 2022).
pheochromocytoma (1 paper, 2020). "In addition, in hypoxia-injured pheochromocytoma cells, up-regulated MEG3 (maternally expressed gene 3) could recruit methylation proteins DNMT3a, DNMT3b and MBD1 to facilitate TIMP2 promoter methylation, which in turn inhibited the expression of this cell cycle arrest inducer TIMP2." (PMID 32370770, 2020).
pituitary apoplexy (1 paper, 2022). A rare, potentially life-threatening disorder caused by acute ischemic infarction or hemorrhage in the pituitary gland. "No evident correlation was found between expression levels of MMP9, MMP2, TIMP2, and PTTG1 and clinical features of PAs, including gender, age, compression symptoms, pituitary apoplexy, tumor texture, resection degree, and recurrence." (PMID 36052250, 2022).
pituitary carcinoma (1 paper, 2020). A primary or metastatic malignant neoplasm affecting the pituitary gland. "In their study, they suggest that miR-17-5p is involved in pituitary carcinoma metastasis, attenuating target genes such as PTEN, a tumour suppressor gene, and TIMP2, involved in inhibiting the degradation of the extracellular matrix and basement membrane." (PMID 32316225, 2020).
Plantar Fasciitis (1 paper, 2025). Inflammation of the plantar fascia (aponeurosis) on the bottom of the foot causing heel pain. "The presence of bioactive molecules such as TIMP-2 and sTNF-RI within EVs further supports their role in counteracting the pathological processes underlying plantar fasciitis." (PMID 40722604, 2025). "TIMP-2 can play a crucial role in inhibiting the pathogenesis of plantar fasciitis by regulating the activity of matrix metalloproteinases (MMPs)." (PMID 40722604, 2025). "This protective mechanism suggests that TIMP-2 could be a potential therapeutic target for plantar fasciitis, helping to restore tissue homeostasis and reduce chronic pain and dysfunction." (PMID 40722604, 2025).
primary lymphedema (1 paper, 2024). A congenital condition that results in swelling in the arms or legs, and can occur during adolescence or adulthood. "It was shown that, in primary lymphedema, genotypes associated with low MMP2 and TIMP2 in serum and tissue fluid are detected, while in secondary lymphedema, other associations of the production levels with combined genetic traits are observed." (PMID 39027126, 2024).
Pulmonary hypoplasia (1 paper, 2013). "SHAM fetuses showed neither real pulmonary hypoplasia nor significant changes in elastin deposition, but sensitive qPCR could detect differences for TNC, TIMP2, and MMP2/TIMP1 ratio." (PMID 23840910, 2013).
pulmonary TB (1 paper, 2021). "MMP-1 and its activator MMP-3 were found to be related to the TB disease severity and treatment efficacy, while MMP-13 together with TIMP-2 were proved to be potential indicators of extra-pulmonary TB in adults." (PMID 33923293, 2021).
pyometra (1 paper, 2026). "This prospective cross-sectional blinded study evaluated whether urinary TIMP-2 and IGFBP7 reflect histopathological renal injury severity in 27 clinically non-azotemic female dogs with pyometra and systemic inflammatory response syndrome (SIRS)." (PMID 41884299, 2026).
renal carcinoma (1 paper, 2016). A carcinoma arising from the epithelium of the renal parenchyma or the renal pelvis. "TIMP-1 over-expression radio-sensitizes the renal cancer cells to gamma radiation and also shows elevation of TIMP-2 protein level as well as decrease of MMP-2 activity." (PMID 27659937, 2016).